SLC25A12 (solute carrier family 25 member 12)
Diseases named in the same sentence as SLC25A12 in open-access papers (continued):
Sharing a sentence is not in itself a finding about the gene and the disease.
sarcopenia (1 paper, 2025). Progressive decline in muscle mass due to aging which results in decreased functional capacity of muscles. "Additionally, downregulation of SLC25A12 expression has been associated with age-related muscle dysfunction, indicating its potential role in sarcopenia." (PMID 41463417, 2025). "These analyses highlighted SLC25A12 and PABPC4 as potential crucial diagnostic biomarkers for sarcopenia." (PMID 41463417, 2025). "In conclusion, SLC25A12 and PABPC4 are promising biomarkers linking copper metabolism dysregulation with sarcopenia, offering potential targets for diagnosis and therapy." (PMID 41463417, 2025). "Diagnostic performance analysis demonstrated strong predictive value for SLC25A12 (AUC = 0.879) and PABPC4 (AUC = 0.858), and RT-qPCR confirmed their downregulation in the sarcopenia cell model (p < 0.01)." (PMID 41463417, 2025).
uterine corpus endometrial carcinoma (1 paper, 2022). A endometrial carcinoma (disease) that involves the body of uterus. "Almost all SLC25s had high mutation frequency in uterine corpus endometrial carcinoma, including SLC25A12, SLC25A13, SLC25A14, SLC25A23, SLC25A24, and SLC25A25." (PMID 36254139, 2022).
vision disorder (1 paper, 2023). Any impairment to the vision. "Among the novel GWAS-identified associations with AL, our study revealed potential candidate genes, including SLC25A12, BMP3, RGR, RBFOX1, and MYO5B, which have all been linked to visual function or eye development and have been implicated in vision disorders." (PMID 37351342, 2023).
tumor (11 papers, 2015 to 2023). "Loss of SLC25A12 impairs the cytosolic aspartate levels, NAD+/NADH ratio, mitochondrial respiration, and tumor growth." (PMID 36698888, 2022). "For six of the genes (CCT5, CD72, COL10A1, FAM177A1, SLC25A12 and TDP1), we were unable to identify a correlation (i.e. concordance) between the copy number alteration and gene expression in six of the tumour samples tested." (PMID 25884485, 2015). "Importantly, silencing of another element of the MAS, aspartate glutamate carrier 1 (SLC25A12), significantly reduced tumour growth by disrupting the NAD+/NADH ratio and aspartate levels." (PMID 34932167, 2021). "Although expression of neither of the two antiporters, SLC25A12 and 13, was increased in SDH-deficient cells, protein expression of SLC25A13 was noted as significantly upregulated in SDH-deficient tumours." (PMID 26522426, 2015). "Lack of SLC25A12, an important component of the malate-aspartate carrier, impairs cytosolic aspartate levels, NAD+/NADH ratio, mitochondrial respiration, and tumor growth, which is considered to be related with metabolism." (PMID 35646664, 2022).
cancer (4 papers, 2020 to 2023). A tumor composed of atypical neoplastic, often pleomorphic cells that invade other tissues. "There was a significant positive correlation between the expression of the TGF β signaling pathway and NOS2 and between cancer pathways and SLC25A12." (PMID 37954858, 2023).
neurological disease (4 papers, 2019 to 2025). "Aspartate-glutamate carrier 1 (AGC1) deficiency is a rare neurological disease caused by mutations in the solute carrier family 25 member 12 (SLC25A12) gene, encoding for the mitochondrial aspartate-glutamate carrier isoform 1 (AGC1)." (PMID 31514314, 2019).
genetic disease (1 paper, 2024). "In the brain, mutations in SLC25A12 gene, encoding for AGC1, cause an ultra-rare genetic disease, reported as a neurodevelopmental encephalopathy, whose symptoms include global hypomyelination, arrested psychomotor development, hypotonia and seizures." (PMID 38553684, 2024).
SLC25A12 also shares sentences with these, for which no sentence is quoted: infantile epileptic encephalopathy (2 papers); inflammatory myopathy (2); brain disorder (1); breast invasive cancer (1); bulimia nervosa (1); cerebellar degeneration (1); colon adenocarcinoma (1); colon cancer (1); depression (1); Desminopathy (1); developmental and epileptic encephalopathy (1); developmental arrest (1); Dystonia (1); Encephalopathy (1); endocervical adenocarcinoma (1); insulinoma (1); mitochondrial disease (1); movement disorder (1); prostate adenocarcinoma (1); skin cancer (1).